TLR4 (toll like receptor 4)
Diseases named in the same sentence as TLR4 in open-access papers (continued):
Sharing a sentence is not in itself a finding about the gene and the disease.
primary biliary cirrhosis (3 papers, 2010 to 2021). "Type 1 IFN may be implicated in the pathogenesis of autoimmunity in primary biliary cirrhosis and is induced by TLR-3, TLR-4, TLR-7, and TLR-9." (PMID 22114589, 2011). "In primary biliary cirrhosis, TLR4 is expressed in bile duct epithelial cells and periportal hepatocytes, and may be involved in the inflammation and tissue destructive process of bile ducts and the interface hepatitis of primary biliary cirrhosis (PBC)." (PMID 20964825, 2010).
psoriasis vulgaris (3 papers, 2017 to 2024). Plaque psoriasis is the most common presentation of psoriasis. "Serum levels of HMGB1, TLR4, IL‐23, and IL‐17A were quantified in 50 patients with moderate‐to‐severe plaque psoriasis and 30 healthy controls." (PMID 38414294, 2024). "Expression levels of serum HMGB1, TLR4, IL‐23, and IL‐17A in patients with psoriasis vulgaris and healthy control, which are denoted by (x ̄ ± s) or M (P25, P75)." (PMID 38414294, 2024).
psychosis (3 papers, 2019 to 2023). "Other changes in baseline TLR4 expression and TLR4 downregulation in response to LPS were also observed in monocytes from SCZ with tardive dyskinesia and in those from patients with first episode of psychosis." (PMID 37626909, 2023).
Pulmonary hemorrhage (3 papers, 2013 to 2025). Pulmonary hemorrhage is a bleeding within the lungs. "HE staining also revealed pulmonary hemorrhage and mild-to-moderate inflammatory infiltration and edema of the intra-alveolar septa in TLR4−/− and WT mice." (PMID 28536433, 2017).
Respiratory Syncytial Virus Infection (3 papers, 2013 to 2024). "Indeed, TLR4*G allele was associated to an increased risk of infections, and mainly to Respiratory Syncytial Virus infections in infants and to pneumococcal and Candida Albicans infections." (PMID 24252506, 2013).
Right ventricular hypertrophy (3 papers, 2017 to 2025). In this case the right ventricle is more muscular than normal, causing a characteristic boot-shaped (coeur-en-sabot) appearance as seen on anterior- posterior chest x-rays. "Cinnamaldehyde, a natural TLR4 inhibitor, alleviates hypoxia-induced PAH in vivo by suppressing the TLR4/NF-κB/HIF-1α pathway, reducing right ventricular hypertrophy and collagen deposition." (PMID 41303627, 2025).
sarcoma (3 papers, 2014 to 2024). A usually aggressive malignant neoplasm of the soft tissue or bone. "We performed TLR4 immunohistochemical analysis across multiple histologic subtypes of banked untreated sarcomas (n = 34); the mean positivity rate was 59% (range, 0%-100%) (eFigure 7A-B in Supplement 2)." (PMID 37824131, 2023). "Our results with CpG+RT and the initial clinical trial of a TLR4 agonist with RT demonstrate the potential effectiveness of TLR agonists and radiotherapy in treating sarcomas." (PMID 39133651, 2024).
Sciatica (3 papers, 2021 to 2023). Pain in the lower back and hip radiating in the distribution of the sciatic nerve. "Since ferulic acid can alleviate sciatica by inhibiting neuroinflammation, promoting sciatic nerve repair and exerting an analgesic effect via the TLR4/NF‐κB pathway, ferulic acid might be developed as a novel therapeutic drug." (PMID 36601662, 2023). "RNA sequencing showed that TLR4/NF‐κB pathway is involved in the mechanism of sciatica." (PMID 36601662, 2023). "Ferulic acid can alleviate sciatica in CCI rats and inhibit neuroinflammation, promote sciatic nerve repair and exert an analgesic effect via the TLR4/NF‐κB pathway." (PMID 36601662, 2023). "The PPI network suggested that TLR4, MMP9, MPO, CAMP, RETN, TLR5, and IL1RN were key genes in the dysregulation of genes in the peripheral blood of patients with sciatica." (PMID 33573686, 2021). "Consistent with the microarray data, the expression levels of the key genes (TLR4, MMP9, MPO, CAMP, RETN and TLR5) were significantly increased in patients with sciatica compared with healthy controls." (PMID 33535986, 2021). "Combining these studies, a potential link between TLR4, MMP9, MPO, CAMP, RETN, and sciatica can be established, but microarray analysis showed that the expression of these genes was not changed after integrated TCM treatment." (PMID 33573686, 2021). "Network analysis identified TLR4, MMP9, MPO, CAMP, RETN and TLR5 as key genes contributing to the dysregulation of genes in the peripheral blood of patients with sciatica." (PMID 33535986, 2021). "Bioinformatic analysis revealed that most of the DEGs-baseline were related to immunity and the inflammatory response and that TLR4, MMP9, MPO, CAMP, RETN, TLR5, and IL1RN were key genes involved in the dysregulation of genes in the peripheral blood of patients with sciatica." (PMID 33573686, 2021).
serous ovarian carcinoma (3 papers, 2018 to 2020). "OVCAR-3 cells due to their TLR4 positivity and as a representative model of serous ovarian cancer were subsequently transfected with siRNA targeting TLR4 or MAD2 and then TLR4, MAD2 and MyD88 expression levels were assessed." (PMID 33370338, 2020).
Sleep apnea (3 papers, 2013 to 2017). An intermittent cessation of airflow at the mouth and nose during sleep is known as sleep apnea. "Despite these limitations, as a practical point of view, the whole body is exposed to hypoxia during sleep apnea, and TLR4 in various cells is likely to be involved in the numerous complications of sleep apnea." (PMID 25873766, 2015). "There are therefore similarities between these clinical findings and our experimental results suggesting that targeting TLR4/NFκB pathway could provide further therapeutic options for sleep apnea patients." (PMID 25873766, 2015). "TLR4 expression and activity is increased on monocytes from patients with sleep apnea, and ligands for TLR4 are increased in the serum of children with sleep apnea." (PMID 24324707, 2013).
soft tissue sarcoma (3 papers, 2022 to 2024). A malignant neoplasm arising from muscle tissue, adipose tissue, blood vessels, fibrous tissue, or other supportive tissues excluding the bones. "Is intratumoral toll-like receptor 4 agonist glycopyranosyl lipid A in stable-emulsion formulation (GLA-SE) injection with radiotherapy an effective and feasible treatment for patients with advanced soft tissue sarcoma (STS)?" (PMID 37824131, 2023).
Splenomegaly (3 papers, 2020 to 2021). Abnormal increased size of the spleen. "Next, we investigated the potential impact of TLR4 on LPS-induced splenomegaly and observed that TLR4 deficiency almost prevented splenomegaly and increased splenic friability in LPS-treated mice." (PMID 33234677, 2021). "Because TLR4 is the receptor of LPS, we next investigated whether RAP99-LPS-mediated weight loss and splenomegaly are dependent on TLR4." (PMID 34113349, 2021). "However, injections of RAP99-LPS caused splenomegaly and increased immune cell numbers in C57BL/6 mice but not in C3H/HeJ mice, suggesting that RAP99-LPS stimulates immune cells via TLR4." (PMID 34113349, 2021).
T cell lymphoma (3 papers, 2018 to 2022). "The expression levels of TLR1, TLR4, TLR7, and TLR9 increased in the LNs of patients with AOSD compared to that in reactive LN or T cell lymphoma." (PMID 35715478, 2022). "The expression levels of TLR1, TLR4, TLR7, and TLR9 were higher in LNs of patients with AOSD than in those with T cell lymphoma and reactive lymphadenopathy." (PMID 35715478, 2022). "The expression levels of TLR1, TLR4, TLR7, and TLR9 were higher in LNs of patients with AOSD than in LNs of those with T cell lymphoma and reactive lymphadenopathy." (PMID 35715478, 2022). "The expression level of TLR2 was similar in LNs from patients with T cell lymphoma and AOSD; however, TLR1, TLR4, TLR7, and TLR9 expression levels were higher in the LNs of patients with AOSD than in T cell lymphoma." (PMID 35715478, 2022). "Jurkat cells (a human CD4+ T cell lymphoma line) have been shown to express most TLRs, and 2G5 cell line in particular has been previously checked for surface expression of TLR2 and TLR4." (PMID 30500820, 2018). "Furthermore, the percentage of inflammatory cells expressing TLR4, TLR7, and TLR9 in LNs from patients with AOSD was significantly greater than that in patients with T cell lymphoma (p = 0.001) and reactive LNs (p = 0.012)." (PMID 35715478, 2022).
uremia (3 papers, 2023 to 2025). A clinical syndrome associated with the retention of renal waste products or uremic toxins in the blood. "Toll-like receptor 4 (TLR4) can detect endogenous danger-associated molecular patterns generated or retained in blood in uremia and induce a sterile muscle inflammatory response via NF-κB in myocytes." (PMID 37447158, 2023). "To investigate whether uremia-associated circulating factors stimulate TLR4 signaling, we treated C2C12 myotubes with uremic serum." (PMID 37447158, 2023). "Collectively, TLR4 up-regulation in muscle appeared to be a component of the stress response that took place in uremia." (PMID 37447158, 2023). "TLR4 activation is another possible target for approaches, either dietary or pharmacological, to disrupt the feed-forward loop of inflammation and wasting in uremia." (PMID 37447158, 2023).
urticaria (3 papers, 2025 to 2026). A vascular reaction of the skin characterized by erythema and wheal formation due to localized increase of vascular permeability. "Microarray analyses have identified IL-6, TNF-α, NF-κB, and TLR-4 as pivotal genes in urticaria pathogenesis." (PMID 40490797, 2025). "In an ovalbumin (OVA)-induced urticaria murine model, LG-1 administration demonstrated marked reductions in serum UA and hypoxanthine concentrations, alleviated clinical manifestations, and suppressed inflammation via TLR4-NF-κB pathway inhibition." (PMID 41703989, 2026).
vaginitis (3 papers, 2024 to 2026). A non-infectious or infectious inflammatory process affecting the vagina. "Τhe distribution of TLR2 Arg753Gln and TLR4 Asp299Gly/Thr399Ile polymorphisms in Greek women, including RVVC (n = 63), first-episode VVC (n = 37), Gardnerella vaginalis vaginitis (GV, n = 36) patients, and healthy controls (n = 61), was investigated using TaqMan SNP genotyping." (PMID 41900485, 2026). "Additionally, the study elucidated that BEPD regulates vaginitis and enhances vaginal barrier function in VVC mice by inhibiting the release of S100A8/A9 and downregulating the TLR4/MyD88/NF-κB signaling pathway." (PMID 38794163, 2024).
ZIKV infection (3 papers, 2017 to 2019). "In view of our results showing that other TLRs, such as TLR4, TLR8 and TLR9, are upregulated during ZIKV infection, in particular with the ZIKVAs strain, additional studies are needed to determine the precise involvement of TLR activation in ZIKV pathogenicity." (PMID 31282298, 2019).
abdominal aortic aneurysm (2 papers, 2016 to 2021). Enlargement and ballooning of the vessel that supplies arterial blood to the abdomen, pelvis and legs. "Evidence suggested that blockade of TLR4 signaling may confer protection against abdominal aortic aneurysm (AAA)." (PMID 26741694, 2016). "Toll-like receptor 4 (TLR4) and matrix metalloproteinase 9 (MMP9) have been investigated to play significant roles in the formation of abdominal aortic aneurysm (AAA)." (PMID 34348653, 2021).
actinic keratosis (2 papers, 2021). A precancerous lesion of the skin composed of atypical keratinocytes. "Expression of TLR4 progressively increases in in sun-damaged skin and actinic keratosis from patient matched samples." (PMID 34771569, 2021).
acute disseminated encephalomyelitis (2 papers, 2020 to 2021). Acute disseminated encephalomyelitis (ADEM) is a demyelinating disorder of the central nervous system. "This study investigated the possible role of local immune changes and the activation state of the HMGB1/TLR4/Nf-κB/IL-6 pathway at the maternal–fetal interface during pregnancy in the pathogenesis of acute disseminated encephalomyelitis (ADEM)." (PMID 33597947, 2020). "We found increased levels of AQP4 in the placenta and fetal membrane in a patient with acute disseminated encephalomyelitis onset in pregnancy as compared to that in a healthy control; this may be due to the activation of the HMGB1/TLR4/Nf-kB/IL-6 pathway." (PMID 35069584, 2021).
acute GVHD (2 papers, 2011 to 2022). "Some researchers have reported that mutations in the TLR4 gene were associated with an increased risk of severe acute GVHD." (PMID 22025895, 2011). "Furthermore, both animal studies and studies of transplant recipients suggest that TLR4 expression/ligation is involved in the development of acute GVHD both in the skin, liver and gastrointestinal tract." (PMID 35163998, 2022). "Thus, TLR4 seems to be involved in posttranspant immunoregulation and the development of acute GVHD, an important risk factor for of non-relapse mortality." (PMID 35163998, 2022).
Acute otitis media (2 papers, 2012 to 2020). Acute otitis media is a short and generally painful infection of the middle ear. "When NTHi was injected in the middle ear of TLR4 mutant mice C3H/HeJ, the severity of acute otitis media was prolonged to 48 hours compared to control mice." (PMID 22662179, 2012). "Blocking the activity of MIF by its antagonist 3-(4-hydroxyphenyl)-4,5-dihydro-5-isoxazole acetic acid methyl ester (ISO-1) could reduce the inflammation in acute otitis media mice in which process TLR-4 and NF-κB were involved." (PMID 32964038, 2020). "It has been found that blocking the activity of MIF by ISO-1 could reduce the inflammation in acute otitis media mice in which process TLR-4 and NF-κB were involved." (PMID 32964038, 2020).
acute pharyngitis (2 papers, 2021 to 2024). An acute and painful inflammatory process that affects the pharynx. "Resveratrol was shown to inhibit the protein expression of TLR4, MyD88, and p‐NF‐κB while increasing the abundance of p‐IκB in animal models of acute pharyngitis." (PMID 38378891, 2024). "The results indicated that S. oblata could alleviate ammonia-induced acute pharyngitis by inhibiting the activation of TLR4/NF-κB/MAPK and NLRP3 inflammasome signaling pathways." (PMID 34925529, 2021).
adenoid hypertrophy (2 papers, 2022 to 2025). "Furthermore, prior works showed that the MBL2 (SNP 49 C/T rs5030737) gene polymorphism; the AG + GG and AG genotypes at TLR4-D299G; Ugrp2; and the 2R, 2R, Il-1Ra and T, and T IL-1b genotypes were associated with an increased risk of developing adenoid hypertrophy." (PMID 35207552, 2022).
Adenomatous polyposis coli (2 papers, 2016 to 2018). "The role of TLR signalling in intestinal tumorigenesis has been studied through the crossing of myeloid differentiation primary response 88 (MyD88)‐deficient mice that have impaired TLR4 signalling, with Apc (ApcMin/+) mice that mimic sporadic cancer and familial adenomatous polyposis." (PMID 30348892, 2018).
adult-onset Still disease (2 papers, 2019 to 2022). A rare inflammatory multisystem disorder characterized clinically by fever of unknown origin, arthralgia or arthritis, hyperleucocytosis, and typical skin rash. "This study investigated the role of Toll-like receptor 1 (TLR1), TLR2, TLR4, TLR7, and TLR9 in patients with adult-onset Still’s disease (AOSD)." (PMID 35715478, 2022).
aortic valve calcification (2 papers, 2014 to 2017). "The pro-osteogenic effect of oxLDL and its interaction with a TLR4 agonist indicate that oxLDL plays a role in aortic valve calcification associated with CAVD." (PMID 24810405, 2014).
Arterial thrombosis (2 papers, 2019 to 2023). The formation of a blood clot inside an artery. "An experimental study of arterial thrombosis comparing wild-type with TLR-4-deficient mice treated with APLA showed that TLR-4 modulates APLA-mediated prothrombotic effects by increasing monocyte production of tissue factor." (PMID 30616644, 2019). "It has been shown that atrial thrombogenesis (which causes thromboembolic stroke) and arterial thrombosis (causes ACS) were related to increased LPS-associated signalling via endothelial and platelet TLR4." (PMID 36672684, 2023).
Ataxia (2 papers, 2020 to 2024). Ataxia refers to impaired coordination of voluntary muscle movement. "Additional research is required to elucidate the precise pathogenic pathway from TLR4 insufficiency to ataxia." (PMID 39147737, 2024). "A loss-of-function BK channel mutation (BKG354S) was found to cause mitochondrial impairment and progressive cerebellar ataxia in patients, so we examined if mitochondria are impaired by PN-specific TLR4 knockout by transmission electron microscopy." (PMID 39147737, 2024). "This study thus provides evidence that TLR4 regulates PN function through a non-immune pathway, and that loss of this regulation results in irregular firing, ultimately leading to cerebellar ataxia." (PMID 39147737, 2024). "In this study, we demonstrate the involvement of TLR4 in non-immune pathway(s) that protect against cerebellar ataxia by maintaining the normal functions of PNs." (PMID 39147737, 2024).
autoimmune thyroid disease (2 papers, 2021 to 2022). Inflammatory disease of the thyroid gland due to autoimmune responses leading to lymphocytic infiltration of the gland. "In 2017, a study investigated on the association of polymorphisms of TLR4 and TLR9 with autoimmune thyroid disease in Korean pediatric patients found that women with GD exhibited higher frequencies of the TLR4 rs10759932 T allele and rs1927911 CC genotype compared to controls." (PMID 33981318, 2021). "In the context of autoimmune thyroid disease, expression of TLR2 and TLR4 positive T-cells and B-cells were higher in the peripheral blood of Graves’s disease patients compared to normal controls, and the proportion significantly decreases after obtaining euthyroid status." (PMID 36521376, 2022).
autonomic dysfunction (2 papers, 2015 to 2025). "TLR4 itself has been linked to autonomic dysfunction: In rats, the activation of TLR4 (induced by injection of LPS, a specific ligand for TLR4) resulted in autonomic dysfunction, characterized by decreased heart rate variability and increased plasma norepinephrine release." (PMID 40362287, 2025). "We examined the role of TLR4 in autonomic dysfunction and the contribution of ER stress." (PMID 25811788, 2015). "The effects induced by LPS were abolished with pretreatment with TLR4 blocker VIPER, indicating a direct role for LPS-induced autonomic dysfunction." (PMID 25811788, 2015).
B-cell lymphoma (2 papers, 2020). "TLR4 expression on tumor cells may therefore be biomarker for identifying patients with B-cell lymphomas susceptible to IT G100 treatment." (PMID 32974162, 2020). "In the A20 model, direct activation of B-lymphoma cells with G100 is sufficient to induce protective CD8 T-cell responses and TLR4 expressing human B-cell lymphomas may be amenable to this therapy as well." (PMID 32974162, 2020). "In the field of oncology research, adverse effects from TLR immunotherapy have been linked to unintended expansion of adaptive leukocytes, such in B-cell lymphoma, where activation of TLR4 MyD88-dependent signaling may exacerbate the disease." (PMID 33679711, 2020). "Using the murine A20 B-cell lymphoma, we investigated the effect of IT G100 on the TME and its dependency on TLR4 expression of the tumor cells." (PMID 32974162, 2020). "Toll-like receptor 4 (TLR4) is widely expressed on immune cells in the mouse, especially macrophages and dendritic cells, as well as on B-cells and B-cell lymphomas." (PMID 32974162, 2020).
bladder tumors (2 papers, 2023 to 2025). "The expression levels of TLR4, TGF-β1, IFN-γ, and TNF-α were evaluated in samples of urinary bladder tumors and unaffected adjacent tissue from 50 patients." (PMID 40778061, 2023).